FADD (Fas associated via death domain)
Diseases named in the same sentence as FADD in open-access papers (continued):
Sharing a sentence is not in itself a finding about the gene and the disease.
cancer (continued). "Hence, it is clear that deficiency of FADD, an essential component in mediating extrinsic apoptotic signaling, partially protects cancer cells from induction of apoptosis by CFZ, indicating that activation of the extrinsic apoptotic pathway contributes to CFZ-induced apoptosis." (PMID 26009898, 2015). "Due to its effects on various aspects of cancer cell behavior, including proliferation, apoptosis, the cell cycle, autophagy, inflammation, and drug resistance, dysregulation in FADD activity leads to the progression of cancer." (PMID 40141789, 2025). "Numerous illnesses, including cancer, are strongly correlated with disruption in the function of the FADD protein." (PMID 40141789, 2025). "Our results also reveal that the adaptor protein FADD is essential for both NF-κB activation and IL-8 induction in cancer cells experiencing metabolic stress due to glutamine starvation, as FADD silencing by siRNA significantly suppressed both processes." (PMID 40683891, 2025). "Consistently, the intracellular delivery of FADD protein in cancer cells recovers apoptotic signaling, increasing cell death." (PMID 38891056, 2024). "The phosphorylation of cFLIPL and cFLIPS has been observed in various cell lines, inhibiting their interaction with the adaptor molecule FADD and sensitizing cancer cells to apoptosis." (PMID 38542202, 2024). "Meanwhile, we conducted biological experiments to verify that FADD enhanced the proliferation, migration and invasion of HNSCC cancer cells, indicating that FADD showed promising diagnostic and prognostic significance in HNSCC." (PMID 38684755, 2024). "The involvement of FADD, cFLIP, caspase-1/-8 in programmed pyroptosis, apoptosis, and necroptosis represents a complex puzzle within the realms of inflammation and cancer." (PMID 38542202, 2024). "Our findings indicate that cancer cell lines sensitive to UNE-C1 exhibit high expression of both FADD and TLR2." (PMID 39669578, 2024). "A recent review summarized the role of FADD in cancer progression and discusses clinical implications as a biomarker and therapeutic target for cancer patients." (PMID 39654143, 2024). "Although the expression of FADD is a contentious topic in various cancer types, the precise molecular mechanisms remain incompletely understood." (PMID 38542202, 2024). "Conversely, dysregulation of FADD expression leads to a range of pathological outcomes, such as cancer, autoimmune disorders, type 2 diabetes, and inflammatory diseases." (PMID 38542202, 2024). "Dysregulated FADD expression, including overexpression and downregulation, has been documented in various types of cancer." (PMID 38542202, 2024). "Recent studies have reported that the FAS-associated death domain (FADD) is critical in the regulation of cancer cell proliferation, and the suppression of FADD expression is a mechanism adopted by cancer cells to escape from apoptosis." (PMID 38891056, 2024). "In fact, mechanistically evasion of apoptosis through low expression of FADD and elevated expression of cFLIP attributes inhibition of DR-mediated apoptosis and favors developing drug resistance in cancer cells." (PMID 38542202, 2024). "In cancer cells, cFLIP occupies the majority of FADD, which serves as a common docking site for both procaspase-8 and cFLIP through DED interactions." (PMID 38542202, 2024). "Numerous research results suggest the clinical significance of FADD as a therapeutic target for cancers." (PMID 38757752, 2024). "Investigating the role of FADD in developmental processes and cancer biology is a compelling area of research." (PMID 38542202, 2024). "In our previous study, we demonstrated the resistance of Jurkat cells deficient in FADD and/or executioner caspases (FADD-/- and CASP3/7/6-/- cells) on common anti-cancer drugs." (PMID 37895085, 2023). "For instance, FADD plays a significant role in cancer metastasis, the spread of cancer cells to distant organs." (PMID 37888480, 2023).
cancer (continued). "Studies have shown that FADD amplification is more common in HNSCC than in other cancers, with upregulation of FADD in HNSCC cell lines and minimal expression of BIRC3." (PMID 36600313, 2023). "FADD is a widely studied regulator of apoptosis, and recent novel findings propose a close relationship between FADD and cancer immunity." (PMID 37671047, 2023). "First, RTA dh404 promoted or inhibited genes associated with cancer cell apoptosis, including three genes (Apaf-1, Bcl-2, and BCL-XL) in GBM8401 cells and three genes (NOXA, BCL-XL, and FADD) in U87MG cells." (PMID 36835414, 2023). "In many cases, excessive activity or inhibition of FADD can have an effect on cell survival, especially in cases of cancer, immune diseases, and viral infections." (PMID 37671047, 2023). "For instance, FADD, FASLG, RIPK1, RIPK3, and TNF were more prone to copy number gain than loss in pan-cancer, but FAS and TLR3 displayed the reverse tendency." (PMID 37351504, 2023). "The mutation rates of copy number variations (CNV) and the expression levels of mRNA were found to be positively correlated in most necroptosis-related genes in 33 cancer types, especially in the cases of FADD and USP22." (PMID 37000317, 2023). "It is known that TRAIL is able to trigger cancer cells’ death by binding the death receptors (DR-4 and DR-5) and by recruiting FADD (Fas Associated Via Death Domain) and caspase-8 to create the death-inducing complex." (PMID 35409187, 2022). "FADD dysregulation contributes to cancer progression by affecting many aspects of cancer cell behavior, including proliferation, apoptosis, cell cycle, autophagy, inflammation, and drug resistance." (PMID 36348274, 2022). "A large number of studies have shown that FADD is involved in cancer progression by regulating apoptosis." (PMID 36348274, 2022). "This review mainly summarizes recent findings on the structure, functions, and regulatory mechanisms of FADD and focuses on its role in cancer progression." (PMID 36348274, 2022). "Taken together, further studies on the mechanisms of FADD involved in drug resistance in distinct types of cancer will be of great benefit to the development of FADD-based therapeutic strategies for patients demonstrating a poor response to chemotherapy." (PMID 36348274, 2022). "An increasing amount of evidence suggests that FADD is a key cell cycle regulator during cancer progression." (PMID 36348274, 2022). "Accumulating evidence has pointed to the involvement of FADD in the regulation of inflammation during cancer progression." (PMID 36348274, 2022). "Overall, it is clear that considering the multifunctional roles of FADD and its dynamics in cancer, it qualifies as a strong candidate marker for diagnosis, prognosis, or therapeutic strategies." (PMID 35227895, 2022). "Accumulating evidence suggests that FADD is a key regulator of cellular proliferation during cancer progression." (PMID 36348274, 2022). "Collectively, fully understanding the mechanisms of FADD in cell cycle regulation would help in the precise use of FADD-based therapeutics in particular types of cancer." (PMID 36348274, 2022). "The clinical implications of FADD as a biomarker and therapeutic target for cancer patients are also discussed." (PMID 36348274, 2022). "FADD dysregulation contributes to cancer progression by influencing many aspects of cancer cell behavior, including proliferation, apoptosis, cell cycle, inflammation, and drug resistance." (PMID 36348274, 2022). "The data from FCM analysis demonstrated that FADD was indispensable to the apoptosis induced by anti-cancer drugs (e.g., DOX and etoposide) in Jurkat cells." (PMID 36348274, 2022). "TNFRSF10B has been shown to interact with FADD, caspase 10, and caspase 8 and induced apoptosis in cancer cells." (PMID 35399006, 2022).
cancer (continued). "Collectively, these findings show that FADD exerts proinflammatory effects in multiple types of cancer, including CRC, CC, and ADC." (PMID 36348274, 2022). "In this review, we mainly summarize recent findings on the structure, functions, and regulatory mechanisms of FADD, focus on its mechanisms of action in cancer progression, and highlight its clinical implications in cancer treatment." (PMID 36348274, 2022). "Taken together, these studies demonstrate that FADD is a crucial regulator of apoptosis during cancer progression." (PMID 36348274, 2022). "Herein, we present a summary of the main modes of FADD regulation, focusing specifically on the mechanisms of FADD regulation in cancer." (PMID 36348274, 2022). "In the following section, we summarize the recent advances regarding the role of FADD in cancer progression." (PMID 36348274, 2022). "Currently, an increasing number of studies suggest that FADD dysregulation contributes to cancer progression." (PMID 36348274, 2022). "FADD also exhibits double-edged effect in targeting the NF-κB signaling pathway in different cancer types." (PMID 36348274, 2022). "The interaction of cancer cells with endogenous TRAIL induces FADD-dependent secretion of CCL2, which polarizes monocytes to the M2 macrophage phenotype." (PMID 34371753, 2021). "In this work, we demonstrate that cell death of Jurkat cells upon treatment with several anti-cancer drugs is FADD dependent." (PMID 33800107, 2021). "In the last decade, FADD has appeared with new roles in innate immunity, inflammation, and cancer development." (PMID 34262870, 2021). "The results from a number of studies of human malignancies have revealed the highly controversial relationship between FADD expression and cancer progression." (PMID 34220946, 2021). "More recently, our group has developed first-in-class small molecule inhibitors capable of disrupting FLIP recruitment to the DISC in cancer cells and inducing caspase-8 and FADD-dependent apoptosis." (PMID 34073507, 2021). "Collectively, our results show that common anti-cancer drugs trigger primarily apoptosis dependent on executioner caspases and FADD." (PMID 33800107, 2021). "The prognostic relevant implications of FADD upregulation (gene amplification, protein phosphorylation and/or overexpression) were early reported in cancer." (PMID 32847023, 2020). "Targeting FADD as a therapeutic candidate would be a promising approach to reinstate apoptosis signaling in cancer cells." (PMID 32961826, 2020). "Given the importance of FADD to resurge apoptosis signaling in cancer cells, earlier studies developed strategies, such as adenoviral and attenuated bacterial-based vectors, for optimal intracellular expression of FADD, and observed induction of apoptosis." (PMID 32961826, 2020). "In summary, the data suggest that the increased cancer stemness seen in cells stimulated through CD95 is dependent on the expression of the two main DISC components FADD and caspase-8." (PMID 31992798, 2020). "The adequate cytosolic expression of FADD is critical to the regulation of cancer cell proliferation." (PMID 32961826, 2020). "In this context, earlier studies demonstrated that low expression of FADD in cancer cells further exacerbates the severity of disease." (PMID 32961826, 2020). "We and others have previously shown that FADD has the potential to reactivate apoptosis, if sufficiently expressed in cancer cells." (PMID 32961826, 2020). "This study provides a novel insight of the molecular mechanism and delivery of FADD protein, which can target cancer cell proliferation and NF-κB activation with subsequent suppression of pro-tumorigenic and proinflammatory signaling." (PMID 32961826, 2020).
cancer (continued). "Cellular status of FADD has been proposed to have clinical relevance as a prognostic indicator for certain cancers." (PMID 32194778, 2020). "Apart from that, cancer cells have constitutive activation of pro-survival NF-κB signaling, which in turn activates anti-apoptotic proteins to impede FADD-mediated apoptosis signaling." (PMID 32961826, 2020). "Our results demonstrate that TAT-mediated intracellular delivery of FADD protein can potentially recite apoptosis signaling with simultaneous regulation of anti-apoptotic and proinflammatory NF-κB signaling activation in cancer cells." (PMID 32961826, 2020). "In contrast, a reduction of FADD has been reported in fewer tumor types, among them hematological malignancies, but also in pathologies different from cancer like dementia." (PMID 31569512, 2019). "In the first two of these cancers, the expression of FADD was correlated with lymph node metastasis and the poor prognosis of patients, and the loss of FADD expression plays an important role in HCC carcinogenesis." (PMID 31443698, 2019). "Future research will likely shed light on the molecular details of FADD functions, thus clarifying its clinical value for each cancer type." (PMID 31569512, 2019). "The authors propose that ING1 downregulation in glioblastoma would result in FADD suppression, leading to apoptosis resistance in cancer cells upon treatment with histone deacetylase inhibitors (HDACi)." (PMID 31569512, 2019). "In any case, many authors agree that FADD levels are a relevant factor to consider in the clinical management of cancer." (PMID 31569512, 2019). "In summary, FADD expression is frequently altered in cancer and its increase is most often related to DNA amplification." (PMID 31569512, 2019). "Considering the various alterations that FADD has been reported to undergo in pathological processes like cancer, many authors support the notion that the FADD level is a relevant factor to consider for diagnosis, prognosis, or therapeutic strategies." (PMID 31569512, 2019). "In this review, we aim to provide detailed, updated information on alterations leading to changes in FADD expression and function in cancer." (PMID 31569512, 2019). "How FADD alterations would contribute to either metabolic switch in cancer still needs to be addressed." (PMID 31569512, 2019). "Regulation of FADD expression in cancer is a complex issue since both overexpression and downregulation have been reported, but the mechanisms underlying such alterations have not been fully unveiled." (PMID 31569512, 2019). "A recent review reported that FADD plays a role in tumorogenesis and is related to poor prognosis in certain cancer patient, and that FADD is a key signaling molecule involved in most signalosome such as inflammasome." (PMID 31741709, 2019). "It was shown that TRAIL-triggered cytokine secretion from TRAIL resistant cancer cells is FADD- and caspase-8 dependent." (PMID 31010082, 2019). "show that endogenous TRAIL signaling in cancer cells induces a FADD-dependent secretome that promotes the accumulation of M2-like immune cells and tumor growth via host CCR2." (PMID 28212753, 2017). "“Pathways in Cancer” and infectious disease pathways were altered containing disease-relevant wnt, FADD, and MEK signaling." (PMID 28828907, 2017). "Here we show that TRAIL-triggered cytokine secretion from TRAIL-resistant cancer cells is FADD dependent and identify the TRAIL-induced secretome to drive monocyte polarization to myeloid-derived suppressor cells (MDSCs) and M2-like macrophages." (PMID 28212753, 2017). "Here we identify a distinct, additional tumor-supportive function of TRAIL-R signaling in cancer cells that requires FADD." (PMID 28212753, 2017). "Recently, amplification of FADD has been observed in many different types of cancer and links to cancer progression." (PMID 27013580, 2016). "First, we examined here, the endogenous expression of FADD and cFLIPL in different origins of cancer and transformed cells." (PMID 26972597, 2016).
cancer (continued). "In another study, overexpression of TIMP-3 in HeLa carcinoma cell line induces a FADD-dependent type II apoptotic signaling pathway." (PMID 27659937, 2016). "The death receptor Fas (APO-1 or CD95) induces apoptosis in many carcinoma cells, which is negatively regulated by anti-apoptotic molecules such as FLIP (Fas-associated death domain (FADD) interleukin-1-converting enzyme (FLICE)-like inhibitory protein)." (PMID 26716643, 2016). "PEA-15 interactions with FADD and procaspase-8 can also be targeted to induced apoptosis of cancer cells." (PMID 26263999, 2015). "We, therefore, propose that AK2 is a negative regulator of tumour growth that activates DUSP26 to suppress cell proliferation by FADD in human cancers." (PMID 24548998, 2014). "The discovery of the ATG5-FADD interaction suggests that decreased expression of either ATG5 or FADD would impact both, autophagy and apoptosis, and therefore, these proteins likely play important and complex roles in cancer development." (PMID 23840208, 2013). "Many reports also reveal the underexpression of FADD in several cancers like thyroid adenoma and acute myeloid leukemia." (PMID 19513126, 2009). "Gene by gene functional analyses have revealed that cyclin D1, FADD and cortactin are potentially able to enhance cancer development." (PMID 18268491, 2008). "Carcinomas with 11q13 amplification showed high protein expression levels in 8/8 cases for cyclin D1, 8/9 cases for FADD and 8/9 for cortactin." (PMID 18268491, 2008). "Immunohistochemical study revealed equal expression of JNK and FADD, but phosphorylated forms were significantly reduced in primary cancer cells with lymph node metastasis." (PMID 16450001, 2006). "As a consequence, a defect in the FADD molecule can contribute to the development of diseases, and particularly cancer." (PMID 15717929, 2005). "In SCC-9 and SCC-25 carcinoma cell lines, carboplatin upregulated FADD protein expression by increasing FADD mRNA." (PMID 15717929, 2005). "Therefore, it is plausible that FOXO1 and FADD have synergistic or antagonistic effects on cell cycle regulation and the response to anticancer drug treatment in cancer cells." (PMID 41596582, 2026). "Finally, we connected HGF, CDK2, FADD, and other proteins to the cancer pathways in the KEGG database." (PMID 40470116, 2025). "FADD has consistently been a prominent research subject for targeted drug therapies, serving as a promising clinical prognostic biomarker and therapeutic target for cancer patients." (PMID 40332106, 2025). "High expression levels of TLR2 and FADD in cancer cells could indicate a favorable response to treatments targeting these pathways, making them promising candidates for personalized immunotherapy strategies." (PMID 39669578, 2024). "The existing literature has unveiled that the expression and prognostic significance of FADD in the context of cancer remains enigmatic, primarily attributable to its pleiotropic effects and dual roles in apoptosis, as well as its involvement in intricate cellular signaling pathways." (PMID 38542202, 2024). "FADD has emerged as a crucial player in the regulation of cancer and inflammatory diseases." (PMID 38542202, 2024). "Inhibition of FADD could reduce cancer cell proliferation, and knockdown of FADD elevated the apoptosis and pyroptosis of cancer cells." (PMID 38684755, 2024). "Our previous research has shown that TAT peptide-conjugated FADD protein is successfully delivered to cancer cells through the caveolar pathway of endocytosis and induces apoptosis signaling, simultaneously targeting pro-tumorigenic and pro-inflammatory NF-κB signaling." (PMID 38542202, 2024). "In our previous study investigating the effect of common anti-cancer drugs on Jurkat cells with knocked-out genes for key players in apoptosis and necroptosis, we revealed the critical importance of FADD protein and executioner caspases in the progression of programmed cell death." (PMID 37895085, 2023).